ETV6 (ETS variant transcription factor 6)
Description:
Transcriptional repressor; binds to the DNA sequence 5'-CCGGAAGT-3'. Plays a role in hematopoiesis and malignant transformation.
Synonyms: Tel; TEL/ABL; THC5
Tractability: Small molecule: a structure with a bound ligand is known; a high-quality ligand is known. Antibody: its Gene Ontology location is reachable by antibodies, with high confidence. PROTAC: UniProt records ubiquitination sites on it; ubiquitination databases record sites on it; its protein half-life has been measured; a small molecule that binds it is known.
Target class: Transcription factor
Gene: Protein-coding gene on chromosome 12 (11,649,623 to 11,895,386, forward strand). Ensembl gene ENSG00000139083.
Subcellular location: Nucleus
Subcellular location (Human Protein Atlas): Nucleoli; Cytosol
Pathways (Reactome):
Disease: Signaling by FLT3 fusion proteins; Signaling by membrane-tethered fusions of PDGFRA or PDGFRB
Gene Ontology:
Molecular function: DNA-binding transcription repressor activity, RNA polymerase II-specific; protein binding; protein domain specific binding; RNA polymerase II transcription regulatory region sequence-specific DNA binding; DNA-binding transcription factor activity; DNA-binding transcription factor activity, RNA polymerase II-specific; DNA binding; DNA-binding transcription activator activity, RNA polymerase II-specific; RNA polymerase II cis-regulatory region sequence-specific DNA binding; sequence-specific DNA binding
Biological process: hematopoietic stem cell proliferation; negative regulation of transcription by RNA polymerase II; cell differentiation; regulation of transcription by RNA polymerase II; positive regulation of transcription by RNA polymerase II; regulation of DNA-templated transcription
Cellular component: chromatin; cytosol; nucleus; plasma membrane
Genetic constraint (gnomAD): Loss-of-function variants: 13 observed, 47.01 expected, observed/expected ratio (o/e) 0.28, 90% interval 0.18 to 0.44. The upper end of that interval is the gene's LOEUF score, 0.44, which puts it in group 1 of 6, group 1 being the genes least tolerant of losing a copy. Missense variants: 440 observed, 585.84 expected, observed/expected ratio (o/e) 0.75, 90% interval 0.69 to 0.81. Synonymous variants: 231 observed, 226.61 expected, observed/expected ratio (o/e) 1.02, 90% interval 0.92 to 1.14.
Gene-disease validity (ClinGen):
ClinGen rates the evidence that ETV6 causes each of these diseases.
thrombocytopenia 5 (autosomal dominant): Definitive. Any thrombocytopenia in which the cause of the disease is a mutation in the ETV6 gene.
Cancer hallmarks: escaping programmed cell death (suppresses); invasion and metastasis (suppresses)
Homologues: Orthologues: chimpanzee ETV6 (99% identical), macaque ETV6 (98% identical), pig ETV6 (98% identical), rabbit ETV6 (96% identical), rat Etv6 (93% identical), dog ETV6 (90% identical), mouse Etv6 (89% identical), guinea pig ETV6 (89% identical), tropical clawed frog etv6 (77% identical). Paralogues in human: ETV7 (34% identical), ETS1 (20% identical), ETS2 (20% identical), FLI1 (19% identical), ERG (18% identical), ETV4 (17% identical), ETV5 (17% identical), SPDEF (16% identical), ETV1 (16% identical), GABPA (16% identical), ELF5 (15% identical), ELF2 (15% identical), and 16 more.
Diseases named in the same sentence as ETV6 in open-access papers:
ETV6 is named in the same sentence as 183 diseases in open-access papers, as found by Europe PMC text mining. Sharing a sentence is not in itself a finding about the gene and the disease. The quoted sentences say what the papers report.
leukemia (133 papers, 2007 to 2026). A malignant (clonal) hematologic disorder, involving hematopoietic stem cells and characterized by the presence of primitive or atypical myeloid or lymphoid cells in the bone marrow and the blood. "In particular, JAK2 fusion partners have been identified alongside PCM1 — including BCR and ETV6— in both B- and T-lineage leukemias, further complicating diagnostic classification and therapeutic decision-making." (PMID 41530508, 2026). "The gene ETV6 has been confirmed to be a genetic susceptibility gene for thrombocytopenia and leukemia." (PMID 40008001, 2025). "The germline ETV6 variant has been described previously in leukemia/lymphoma cases in a family with thrombocytopenia." (PMID 40995433, 2025). "Off-targeting activity of RAG enzymes drives the secondary mutational processes in ETV6::RUNX1 leukemia, causing SVs for example at TBL1XR1 locus, which is associated with inferior outcome." (PMID 40634509, 2025). "ETV6, a transcriptional repressor associated with various types of leukemias, is transiently overexpressed in Day 1 cells, with its levels dropping again in Day 7 cells (Fig. EV5H)." (PMID 39972074, 2025). "In summary, we integrated multiomic data with treatment response profiles to characterize the genetic alterations and biological processes associated with therapy response in pediatric ETV6::RUNX1 leukemia." (PMID 40634509, 2025). "Previous WGS analysis of ETV6::RUNX1 leukemias established a key role for the RAG-driven mutational process in the generation of SV at off-target sites." (PMID 40634509, 2025). "Much work has been undertaken in the paradigmatic pre-leukemia initiated in utero by the ETV6::RUNX1 gene fusion, the commonest single genetic cause of childhood BCP-ALL." (PMID 36959797, 2023). "We further identified well-known large recurrent 12p deletions (≥5 Mb) in ETV6::RUNX1 leukemia, which are associated with biallelic inactivation of the ETV6 gene." (PMID 37469802, 2023). "ETV6 is responsible for encoding a transcriptional repressor, and ETV6 mutations or dysregulated gene expression can lead to the development of leukemia or leukemogenesis." (PMID 36982819, 2023). "A recent study further showed that a frameshift variant of UBA2 was discussed to predispose to ETV6::RUNX1+ leukemia in monozygotic twins." (PMID 37469802, 2023). "It is worth mentioning that secondary mutations in TBL1XR1 have recently been implicated in improving risk stratification, especially in ETV6::RUNX1 leukemia, where mutations led to inferior survival." (PMID 37469802, 2023). "The rearrangement of ETV6-LPXN associated with progression of leukemia through regulating the microenvironment of blasts and involved in the relapse of leukemia has been reported." (PMID 36003793, 2022). "Studies have revealed chromosomal translocations as the major cause of aberrant ETV6 expression in leukemia and various solid tumors." (PMID 36292767, 2022). "Meanwhile, it has been reported that the ETV6 mutations collaborate with other mutations to build their own network structure, which would stimulate the self-renewal of leukemia stem cells." (PMID 36003793, 2022). "Additional cytogenetic alterations often appear with ETV6 mutations, which contain various fusion genes and play a vital role in obtaining information about leukemia genesis and influencing the progression of leukemia." (PMID 36003793, 2022). "Leukemia with ETV6/ABL1 fusions is rare and associated with a poor prognostic outcome, but are sensitive to tyrosine kinase inhibitors." (PMID 34503197, 2021). "We also detected homozygously deleted tumor suppressor genes and tumor suppressor genes with biallelic loss of gene function and a novel expressed fusion gene ETV6-TSL in a sample with mixed lineage leukemia." (PMID 34362951, 2021).
leukemia (continued). "Accordingly, germline mutations in ETV6 are related to familial thrombocytopenia (usually mild) and leukemia predisposition." (PMID 34502524, 2021). "ETV6 is a leukemia-associated gene located on 12p13, which has been shown to play a wide role in hematopoiesis and hematological malignancies." (PMID 32326970, 2020). "The ProteinPaint view embedded in the variant page confirmed that in ETV6, somatic mutations are dominated by loss-of-function mutations across pediatric leukemia, consistent with the tumor suppressor gene model." (PMID 31439692, 2019). "It has been well documented that translocations of Runx1, the essential hematopoiesis factor, with ETO, TEL (ETV6) or other genes cause a wide range of leukemias." (PMID 28407681, 2017). "Children with ALL-related ETV6 variants were significantly older at leukemia diagnosis than others (10.2 years [IQR 5.3-13.8] vs 4.7 years [IQR 3.0-8.7], P=0.017)." (PMID 26522332, 2015). "Consistent with its putative role as a tumor suppressor, examination of the diagnostic leukemia sample in the proband from Kindred 2 revealed retention of the mutant and deletion of the WT ETV6 allele." (PMID 26102509, 2015). "The hyperdiploid leukemia karyotype was strikingly overrepresented in ALL cases harboring germline ETV6 risk variants compared to the wildtype group (9 of 14 cases [64.3%] vs 538 of 2,007 cases [26.8%]; P=0.0050)." (PMID 26522332, 2015). "Children with ALL-relate ETV6 variants had distinct clinical features, suggesting unique leukemia etiology." (PMID 26522332, 2015). "ETV6 encodes an ETS family transcription factor that is frequently rearranged or fused with other genes in human leukemias of myeloid or lymphoid origin." (PMID 26102509, 2015). "This discovery makes possible the pre-symptomatic diagnosis of leukemia susceptibility in families with germline ETV6 mutations, and also provides new information on the causes of leukemia." (PMID 26102509, 2015). "The hyperdiploid leukemia karyotype was strikingly overrepresented in ALL cases harboring germline risk variants in ETV6 compared to the wildtype group (9 [64.3%] of 14 cases vs 538 [26.8%] of 2,007 cases), P=0.0050)." (PMID 26522332, 2015). "Sequencing a panel of genes identified germline ETV6 mutations associated with leukemia and thrombocytopenia in multiple individuals tested." (PMID 26102509, 2015). "ETV6 variants include insertion/deletion mutations and structural variants (deletions, rearrangements) that may lead to truncation and loss of function of ETV6, ultimately contributing to thrombocytopenia and leukemia." (PMID 40008001, 2025). "However, the constitutive activation of Abl by the disruption of its autoinhibition mediated by the translocation to a variety of many genes such as BCR, Tel, and ETV6 is the main cause of the development of different tumor types, including leukemia." (PMID 39123481, 2024). "Modeling ETV6-associated leukemia commonly uses the ETV6-RUNX1 fusion protein." (PMID 37377909, 2023). "ETV6 invalidations are, however, known in leukemia: somatic mutations of ETV6 remain rare in AML, but germline mutations are also possible in the context of thrombocytopenia predisposing to AML, Myelodysplastic Syndromes (MDS), Chronic MyeloMonocytic Leukemia (CMML), B-ALL, or multiple myeloma." (PMID 36077669, 2022). "Deep deletion of ETV6, a transcription-regulating gene, has been previously implicated in leukemias and may play a role in oncogenesis, treatment response, and outcome in pediatric ALL patients." (PMID 36497424, 2022). "Mutations of ARID5B might be a potential cofactor in patients with ETV6-linked leukemia predisposition." (PMID 35870987, 2022). "For instance, GATA1 mutations could affect both megakaryopoiesis and erythropoiesis, whereas variants of RUNX1 and ETV6 are involved in leukemia predisposition." (PMID 34502524, 2021).
leukemia (continued). "The remaining 6 genes are not known to be enriched for point mutations in breast cancer, and may therefore represent specific indel/structural variant driver genes; of these, ETV6 is known to act as a tumor suppressor in leukemias." (PMID 31182087, 2019). "Therefore, children in this age group with myeloid disorders were recommended to be screened for both MLL (mixed lineage leukemia gene) and ETV6 (ETS variant gene 6) rearrangements." (PMID 26294991, 2015). "Our findings highlight a novel role for ETV6 in leukemia predisposition." (PMID 26102509, 2015). "Similarly, experimental characterization is warranted to define the exact function of the potential ALL-related ETV6 variants and to elucidate the molecular pathways by which they influence leukemia formation." (PMID 26522332, 2015). "Similarly, ETV6 is one of the most well-known leukemia-predisposing genes." (PMID 40995433, 2025). "Given that germline mutations of RUNX1 or ETV6 are associated with leukemia with incomplete penetrance, these data suggest somatic alterations of these genes also require additional mutations for leukemia development, which may cooperatively define the immature leukemic phenotypes." (PMID 38212634, 2024). "The substantial proportion of childhood ALL cases carrying ETV6 germline variants of potential pathologic significance highlights the importance of ETV6 as a leukemia predisposition gene and also indicate that inherited susceptibility to ALL may be much more substantial than currently believed." (PMID 26522332, 2015). "This alteration generates the ETV6::RUNX1 (E::R) fusion gene, encoding an aberrant transcription factor that is insufficient to directly cause leukemia, but establishes a clinically silent pre-leukemic progenitor not yet fully characterized." (PMID 41813667, 2026). "Overall, our findings highlight SNV, CNV, and transcriptomic alterations impacting the induction and consolidation treatment response among patients with ETV6::RUNX1 leukemia paving the way for more tailored therapy allocation." (PMID 40634509, 2025). "The four most common leukemia genes in B-ALL children were ETV6/RUNX1, E2A/PBX1, MLL, and BCR/ABL in sequence." (PMID 41195225, 2025). "The reported prevalence of the ETV6::RUNX1 fusion was about 100× higher than the actual leukemia incidence, indicating that the fusion gene is only mildly oncogeneic." (PMID 40243620, 2025). "Consistent with previous studies in ALL, our findings showed that the APOBEC mutational signatures (C → T and C → G conversions) are prevalent in ETV6::RUNX1 leukemia." (PMID 40634509, 2025). "To date, MRD level is the only identified biomarker that predicts treatment failure in ETV6::RUNX1 leukemia." (PMID 40634509, 2025). "ETV6::RUNX1 leukemia is the second most common subtype of childhood B cell acute lymphoblastic leukemia (B-ALL)." (PMID 40634509, 2025). "A large diversity offusion oncogenes was observed, primarily in one tumor, the three most commonbeing: EWSR1::Fli1 (n = 13) observed in Ewing sarcomas, PAX3::FOXO1 (n = 12) inrhabdomyosarcomas, and ETV6::RUNX1 (n = 8) in childhood leukemias." (PMID 40093400, 2025). "Earlier study reported that APOBEC signatures (SBS2 and SBS13) were enriched in ETV6::RUNX1 leukemia." (PMID 40634509, 2025). "ETV6 is identified as an oncogene in various leukemias and myeloproliferative syndromes, functioning as a transcription factor." (PMID 39857780, 2025). "In scRNA-seq data from five ETV6::RUNX1 leukemias from our previous study, A3B expression was the highest in the G2M phase cells compared to other cell cycle phases." (PMID 40634509, 2025). "This study identified prenatal exposure to corticosteroids as a potential risk factor for prenatal ETV6::RUNX1 fusions and, thus, for leukemia development later in life." (PMID 40243620, 2025).
leukemia (continued). "In twins with concordant ETV6::RUNX1-positive leukemia, ALL develops at different times, and postnatal latency can be protracted." (PMID 40243620, 2025). "In this study, we used multiomic data from ETV6::RUNX1 leukemias to identify genomic features predictive of therapy response at disease presentation." (PMID 40634509, 2025). "For the leukemia patients harboring ETV6::RUNX1, an aberrancy in the CLP–pre-pro-B–early-pro-B differentiation axis was observed." (PMID 39945785, 2025). "ETV6 dysfunction has been found to promote inflammation, adversely affecting thrombopoiesis and promoting leukemia development." (PMID 39355256, 2024). "ETV6 is a promiscuity gene that plays a role in the development of various tumors, such as leukemia, lymphoma, secretory carcinoma of the breast, infantile fibrosarcoma, congenital mesoblastic nephroma, and thyroid cancer." (PMID 37251917, 2023). "This means that the cytokine profile seems to be quite specific to those children, who had developed an ETV6::RUNX1-positive leukemia and seems to be influenced by factors other than environmental factors." (PMID 36741356, 2023). "These pathways were also specifically enriched in the transcriptome of ETV6::RUNX1 positive patients indicating a critical role for IGF2BP1 in this leukemia subtype." (PMID 37670323, 2023). "SPIB mRNA transcript levels are low in ETV6::RUNX1+ ALL relative to other leukemia subtypes, as the SPIB gene is directly activated by RUNX1 during B-cell development." (PMID 36766699, 2023). "The results indicated that KYN significantly increased cell proliferation marker expression (cyclin D1, E2F1, and Ki-67), as well as IDO1, TDO2, Ikaros1, AML1, and ETV6 expression, in leukemia cells." (PMID 35687267, 2023). "Functional evaluation of germline ETV6 and FLI1 variants from leukemia and thrombocytopenia patients suggests that the substitution of conserved residues disrupts the protein’s general function." (PMID 37377909, 2023). "With many of these pathways being druggable and a small molecule inhibitor for IGF2BP1 available, our work lays the foundation for novel combinatorial therapeutic approaches in ETV6::RUNX1 positive leukemias." (PMID 37670323, 2023). "In translocations involving MN1, BTL, and PAX5, the DNA-binding domain of ETV6 is part of the leukemogenic fusion protein, which suggests that altered expression of normal ETV6 target genes is involved in the pathogenesis of leukemia." (PMID 36766699, 2023). "ETV6 localized at these longer consecutive GGAA repeats at a higher frequency in Ewing sarcoma than in B lymphocytes or in K-562 leukaemia cells, which express ETV6 (P < 2.2 × 10−16)." (PMID 36658220, 2023). "We compared the frequencies of SVs detected by OGM between the 2 genetic subgroups of BCP-ALL (ETV6::RUNX1+ and HD leukemia, n = 30 each) that occurred in addition to their hallmark events." (PMID 37469802, 2023). "Studies using gene knockouts have demonstrated that ETV6 plays a significant role in chromosomal rearrangements related to leukemia and congenital fibrosarcoma, influencing hematopoiesis, and maintaining the development of vascular networks." (PMID 36914737, 2023). "Overall, our results suggest that IGF2BP1 plays an important role in the pathogenesis of ETV6::RUNX1 leukemia through multiple oncogenic pathways and can be utilized as an ideal therapeutic target for this particular subtype." (PMID 37670323, 2023). "For instance, ETV6, involved in different types of leukemia is downregulated in cytarabine-resistant tissues, and ETV6 knockout cell lines exhibit an increased gene expression of splicing factors." (PMID 37422594, 2023). "ETV6 mutations are rare in MDS (3%) and correlate with shorter survival and a variable predisposition to leukemia." (PMID 36982819, 2023). "The first molecular evidence for a prenatal origin of childhood leukemia arose from twin studies of KMT2A-rearranged and ETV6/RUNX1 leukemia published in the 1990s." (PMID 33968846, 2021).